MTOR (mechanistic target of rapamycin kinase)
Diseases named in the same sentence as MTOR in open-access papers (continued):
Sharing a sentence is not in itself a finding about the gene and the disease.
systemic sclerosis (14 papers, 2018 to 2025). A chronic disorder, possibly autoimmune, marked by excessive production of collagen which results in hardening and thickening of body tissues. "Resveratrol ameliorates BLM-induced skin inflammation and fibrosis in systemic sclerosis mice by activating SIRT1/mTOR signalling." (PMID 37483618, 2023). "The inhibition of mTOR cascade by rapamycin ameliorates the osteopenia phenotype in Fbn1+/− systemic sclerosis (SSc) mice." (PMID 38269088, 2023). "Amelioration of mTOR has been found in fibroblasts from patients with systemic sclerosis and in skin lesions from BLM-treated mice." (PMID 37483618, 2023). "Geniposide can attenuate systemic sclerosis via endothelial cell protection and inhibition of the mTOR pathway." (PMID 34258301, 2021). "The phosphatidylinositol-3-kinase (PI3K)/Akt and the mammalian target of rapamycin (mTOR) pathways are known to play a key role in B-cell activation and fibrosis in systemic sclerosis (SSc)." (PMID 35743222, 2022). "The mTOR pathway is also important in in systemic sclerosis (SSc) pathogenesis because through its signaling in SSc fibroblasts it could mediate the immunoinflammatory process typical of ILD in these patients." (PMID 34299359, 2021).
thymoma (14 papers, 2013 to 2025). A neoplasm arising from the epithelial cells of the thymus. "The expressions of AKT1 and its downstream molecule mTOR in the thymoma microenvironment of thymoma-associated MG patients who did not receive dexamethasone before operation were higher than those in the group receiving dexamethasone before operation." (PMID 37498332, 2024). "For patients with types A and B1/B2 thymoma (n = 9), seven gene mutations, including MTOR, BRCA1, APC, NF1, HRAS, NTRK3, and PTCH1, were detected, and each gene appeared only once in patients with non-TCs+type B3 TETs." (PMID 34307137, 2021). "Beside the deregulation of the Akt/ mTOR pathway, we have identified for the first time PIK3CA mutation in a type B2/B3 thymoma, which may participate to the deregulation of the Akt-mTOR pathway, among others." (PMID 30897085, 2019). "The results showed that the level of AKT1 and mTOR protein in all 5 thymoma patients who received DXMS treatment was lower than that in the non-DXMS group, while the level of apoptosis protein, cleaved caspase-3, showed the opposite trend." (PMID 37498332, 2024). "Statistics showed that the expressions of AKT1 and mTOR in the thymoma TME of the dexamethasone-treated group were lower than those of the non-dexamethasone-treated group." (PMID 37498332, 2024). "Recent studies have reported that EGFR can be expressed in thymoma, which is an important cause of myasthenia gravis, and that EGFR overactivates the downstream PI3K/Akt/mTOR signalling pathway, inhibits apoptosis, and stimulates tumor growth." (PMID 36818231, 2023). "We further tested a variety of PI3K, AKT, and mTOR inhibitors in our thymoma cell line (IU-TAB-1) and found significant activity for several of these agents." (PMID 36330484, 2022). "Further support of targeting the PI3K pathway comes from a Phase II trial in thymoma patients with the mTOR inhibitor, everolimus." (PMID 36330484, 2022). "Different from the normal thymus, both Akt and mTOR were activated in thymomas, and rapamycin, a specific inhibitor of mTOR, was shown to significantly reduce the proliferation of thymoma-derived epithelial cells." (PMID 35159040, 2022). "The PIK3/Akt/mTOR pathway plays a key role in various cancers; interestingly, several phase I/II studies have reported a positive effect of mTOR inhibitors in disease control in thymoma patients." (PMID 30897085, 2019). "Using primary thymic epithelial cells derived from A, AB and B thymomas, we report the dysregulation of the Akt/ mTOR pathway in thymomas and the anti-proliferative effect of rapamycin on thymic epithelial cells." (PMID 30897085, 2019). "In this study, we report the derivation of primary thymic epithelial cell cultures from type A, AB and B thymomas, their phenotypic and genetic characterization as well as the deregulation of the Akt-mTOR pathway and its impact on cell proliferation." (PMID 30897085, 2019). "While only Akt and phospho-Akt were expressed in normal thymuses, both Akt and mTOR were activated in thymomas." (PMID 30897085, 2019). "We demonstrated that the Akt-mTOR pathway was activated in thymomas as well as in thymic epithelial tumor cells derived from type A, AB, and B thymomas." (PMID 30897085, 2019). "The activation of mTOR was reduced by ~90%, ~30% and ~ 50% in thymic epithelial cells respectively derived from AB (3147), B2 (3146) and B2/B3 thymomas." (PMID 30897085, 2019). "Thus, we continued to verify the positive effect of dexamethasone on thymoma-associated MG focusing on the AKT1 and its downstream factor mTOR." (PMID 37498332, 2024). "Importantly, these three thymomas and the derived thymic epithelial cells expressed mTOR and phospho-mTOR." (PMID 30897085, 2019). "Overall, the Akt/ mTOR pathway was activated in A, AB and B thymomas as demonstrated by the detection of phosphorylated Akt, mTOR and P70S6K proteins, with various level of expression that probably reflected the relative frequency of tumoral and non-tumoral cells within the tumors." (PMID 30897085, 2019).
thymoma (continued). "The expression of phospho-mTOR was similar in type A and B3 thymomas and thymic carcinomas." (PMID 27844328, 2017). "The thymoma tissues of the enrolled patients were selected to verify the expression of AKT1 and mTOR." (PMID 37498332, 2024). "An additional study delved into the expression patterns of Akt, mTOR, and P70S6K in type A, type B, and type AB thymomas, substantiating the perturbed Akt/mTOR pathway in these thymomas." (PMID 37849766, 2023). "Remarkably, a miRNA cluster located on chromosome 19q13.42 exhibits prominent overexpression in type A and AB thymomas, leading to the activation of the PI3K/AKT/mTOR signaling cascade." (PMID 37849766, 2023). "To determine the role of the Akt/ mTOR pathway in proliferation of tumoral thymic epithelial cells, we analyzed expression of mTOR, Akt and P70S6K in thymic epithelial cells derived from seven patients with A, AB or B thymomas." (PMID 30897085, 2019). "Akt, mTOR and P70S6K were activated in all thymomas, as shown by the detection of phosphorylated proteins." (PMID 30897085, 2019). "Immunohistochemistry was performed to study the expression of ALK, HER2, HER3, MET, phospho-mTOR, p16INK4A, PDGFRA, PDGFRB, PD-L1, PTEN and ROS1 in type A and B3 thymomas and thymic carcinomas." (PMID 27844328, 2017). "Type A and B3 thymoma and thymic carcinoma tissues were stained with antibodies to ALK, HER2, HER3, MET, phospho-mTOR, PDGFRA, PDGFRB, PD-L1, p16INK4A, PTEN and ROS1 to identify potential targets for therapy." (PMID 27844328, 2017). "Since RPS6 is an effector of the AKT/mTOR pathway, we studied expression of its negative regulators PTEN and PIK3R1 but found them up-regulated only slightly (p < 10−3) in B3 thymomas." (PMID 24427739, 2013). "Several investigators suggest that the PI3K/AKT network plays an important role in thymoma growth and may sensitize cells thymic epithelial tumors (TET) to mTOR inhibition." (PMID 36330484, 2022). "Interestingly, we report the activation of Akt, mTOR and P70S6 proteins in primary thymic epithelial cells maintained for short period of time after their derivation from seven AB and B thymomas." (PMID 30897085, 2019). "Our results also confirmed that the expression level of AKT1 and mTOR were decreased and the expression level of the apoptosis-related protein, cleaved-caspase-3, was increased in the TME of thymoma patients using DXMS, which also suggested that DXMS promoted apoptosis of thymoma cells." (PMID 37498332, 2024). "In one of the largest prospective trials evaluating the mTOR inhibitor, everolimus, in recurrent TET (thymoma and thymic carcinoma), five partial and one complete responses were noted in 51 patients (CR + PR =12%) with 3 partial responses occurring in the 32 patients with thymoma." (PMID 36330484, 2022). "Meanwhile the cellular dysregulation of the Akt/ mTOR pathway has not been described in thymomas." (PMID 30897085, 2019). "Meanwhile, the IU-TAB-1- cell line was established from type AB thymoma, with phenotypic and molecular profiling but limited information of derivation protocol and success rate, and subsequent analysis of molecular pathways of interest, including PIK3/ AKT/ mTOR." (PMID 30897085, 2019). "Our study showed that in the thymoma TME, the expressions of AKT1 and mTOR in the non-dexamethasone treatment group were higher than those in the dexamethasone treatment group." (PMID 37498332, 2024). "A large miRNA cluster on chromosome 19q13.42 (C19MC) was shown to be significantly overexpressed in all A and AB TEN and virtually absent in the other thymomas and normal tissues, while overexpression of C19MC activated the oncogenic PI3K/AKT/mTOR pathway." (PMID 35409405, 2022). "We analyzed protein expression and activation of key players of the Akt/ mTOR pathway namely Akt, mTOR, and P70S6K in eleven A, B and AB thymomas as well as in normal thymuses." (PMID 30897085, 2019).
thyroid (14 papers, 2017 to 2025). "A previous study showed that suppressing the PI3K/Akt/mTOR signaling pathway inhibited autophagy in a model of thyroiditis." (PMID 33273957, 2020). "Excessive activation of the PI3K/Akt/mTOR signaling is frequently observed in thyroid tumorigenesis." (PMID 32025215, 2020). "Thyroiditis results in elevation of the mTOR/HIF-1α/HK2/glycolysis pathway in CD4+ T cells." (PMID 34149615, 2021). "C2 exhibited RAS-like tumor characteristics, with a higher thyroid differentiation score (TDS), lower ERK and greater mTOR signaling pathway activation." (PMID 38287330, 2024). "Considered as a thyroid oncogenic pathway, AKT/mTOR pathway is mostly hyperactivated in PTC, particularly in poorly differentiated thyroid cancer." (PMID 32284745, 2020).
thyroid tumor (14 papers, 2013 to 2025). A benign or malignant neoplasm affecting the thyroid gland. "In human thyroid tumors, mTOR also seem to display a more critical role in thyroid tumorigenesis, as it is the most activated pathway, compared to MAPK." (PMID 40711277, 2025). "The patterns of MAPK and mTOR activation in feline thyroid tumors seem to mirror their human counterparts." (PMID 40711277, 2025). "Beyond thyroid tumors, the expression and activation of mTOR and MAPK pathways have been investigated in other feline models, though data remain limited." (PMID 40711277, 2025). "By evaluating the phosphorylation levels of these proteins, we addressed the activation status of MAPK- and mTOR-signaling pathways for the first time in feline thyroid tumors." (PMID 40711277, 2025). "Mutations occurring at the codons 600 of BRAF and 61 of RAS genes are common in human thyroid tumors, with these mutations being the most frequent events that lead to the activation of MAPK- and mTOR-signaling pathways." (PMID 40711277, 2025). "Human thyroid tumors are often characterized by activating point mutations in BRAF, NRAS, HRAS, or KRAS, leading to the overactivation of MAPK- and mTOR-signaling pathways." (PMID 40711277, 2025). "In thyroid tumor cells, intracellular Ca2+ oscillations have been shown to play a role in the regulation of the target of rapamycin (mTOR) pathway, a key signaling pathway involved in cell growth and proliferation." (PMID 37056339, 2023). "Activation of the mTOR serine/threonine protein kinase has been reported in a variety of malignant tumors, including thyroid tumors, with an estimated 70% of all tumors showing mTOR upregulation." (PMID 26294908, 2015). "Furthermore, MAPK- and mTOR-signaling pathways seem to display similar biological roles to those observed in human thyroid tumors." (PMID 40711277, 2025). "Overall, the role of intracellular Ca2+ oscillations in thyroid tumor cell biology and the mTOR pathway is an active area of research, and further studies are needed to fully understand the mechanisms involved and to identify potential therapeutic targets for the treatment of thyroid cancer." (PMID 37056339, 2023). "We hypothesised that this coregulation could be orchestrated by mTOR, which is often deregulated in thyroid tumors." (PMID 23516535, 2013). "In contrast, in human medicine, the molecular characterization of thyroid tumor-ascertained mutations in BRAF, NRAS, HRAS, and KRAS is relevant as they are players implicated in thyroid tumor progression through their activation of MAPK- and mTOR-signaling pathways." (PMID 40711277, 2025). "Similarly, no mutations were found in the MAPK, CDK, and PI3K/AKT/mTOR pathways in thyroid tumors and their brain metastases, which would suggest that a therapy targeting these pathways would not be clinically recommended." (PMID 36507516, 2022). "Studies in thyroid tumors suggest that Metformin increases p AMPK, reduces mTOR phosphorylation, downregulates S6K1/S6 signaling, and inhibits cyclin D1 and c MYC via the mTOR pathway." (PMID 41156128, 2025). "Studies have shown that stimulation of thyroid tumor cells with thyrotropin-releasing hormone (TRH) induces Ca2+ oscillations, which in turn activate the mTOR pathway." (PMID 37056339, 2023). "The phosphoinositide-3-kinase (PI3K)/protein kinase B (AKT)/mechanistic target of rapamycin (mTOR) and mitogen-activated protein kinase (MAPK)/extracellular signal-regulated kinase 1/2 (ERK1/2) cascades are pivotal drivers of thyroid tumor growth, survival, and metastasis." (PMID 41477125, 2025). "Tumourigenesis of thyroid tumours involves dysregulation of cell signalling pathways mitogen-activated protein kinase (MAPK) and phosphatidylinositol-3 kinase (PI3K)/Ak strain transforming (AKT)/mammalian target of rapamycin (mTOR) signalling pathways." (PMID 34062862, 2021).
thyroid tumor (continued). "Thus, we conclude that mTOR is not involved in PLX4720-induced autophagy and it is plausible that V600EBRAF inhibition bypasses mTORC1 complex to enhance autophagy in thyroid tumour cells with this mutation." (PMID 34204950, 2021). "The study aimed to study the AKT / mTOR signaling pathway components, transcriptional and growth factors, as well as steroid hormone receptors and nuclear factors Brn-3α and TRIM16 expression in the tissue of the primary thyroid tumor and metastases, depending on the BRAF- V600E status." (PMID 34319022, 2021). "Further, activation of AMPK by this signaling cascade does not inhibit mTOR activation in our mouse tumors, an FTC cell line, and a subset of human thyroid tumors (which show high AMPK pathway activation)." (PMID 31798532, 2019).
age (13 papers, 2016 to 2025). A temporal measurement of the time period elapsed since an identifiable point in the life cycle of an organism. "This intricate balance between mTOR and autophagy is intimately tied to aging and disease, as excessive mTOR activity and compromised autophagy are associated with age-related pathologies, including neurodegenerative diseases and cancer." (PMID 38463143, 2024). "interestingly, mTOR-inhibitors can be considered as up-regulators of klotho, potentially preventing or delaying the onset of age-related cardiovascular dysfunctions, as suggested by our results." (PMID 33758105, 2021).
atopic dermatitis (13 papers, 2016 to 2025). "The gene levels of AKT, mTOR, and c-Jun were significantly increased in the model group, which demonstrated that the atopic dermatitis microenvironment had been successfully created." (PMID 39861084, 2024). "IL-37 can reverse the manifestation of inflammation in atopic dermatitis by regulating the microbiota and the autophagy signaling pathway via mTOR." (PMID 35163615, 2022). "In addition, increased mTOR phosphorylation in the lesional skin was observed and topical application of rapamycin remarkably improved AD symptoms in skin lesions of murine atopic dermatitis models." (PMID 27239444, 2016). "The mTOR and STAT3 signaling pathways have been known as crucial for maintaining homeostasis of skin barrier in pathophysiology of atopic dermatitis." (PMID 34946332, 2021).
basal cell carcinoma (13 papers, 2008 to 2024). A carcinoma involving the basal cells. "Similar to the PI3K/Akt signal pathway, the pathways in cancer, basal cell carcinoma signaling pathway, mTOR signaling pathway, Wnt signaling pathway and melanogenesis signaling pathway are common cancer-related pathways." (PMID 35898891, 2022). "Among cutaneous cancers, basal cell carcinoma (BCC) and cutaneous squamous cell carcinoma (cSCC) display PI3K/AKT/mTOR signaling hyperactivation, implicated in hyperproliferation, and tumorigenesis, as well as in resistance to apoptosis." (PMID 33996865, 2021). "In addition, highly expressed SOX9 promotes proliferation of basal cell carcinoma by directly transcriptionally regulating mTOR, which is a crossover pathway between hedgehog signaling and PI3K/AKT/mTOR pathways." (PMID 35563098, 2022).
colon adenocarcinoma (13 papers, 2016 to 2024). "Previous studies have demonstrated that BA effectively inhibits the growth of colon adenocarcinoma cell CT26 via promoting autophagy mediated by PI3K/AKT/mTOR signaling." (PMID 36567856, 2022). "For example, we integrated 420 cancer mutations from TCGA for a human PIKK family kinase, MTOR, which is frequently mutated in a variety of cancers, especially uterine corpus endometrial carcinoma (UCEC) and colon adenocarcinoma (COAD)." (PMID 30380109, 2019). "In human colon adenocarcinoma cells, quercetin significantly enhanced the expression of the endocannabinoid receptor (CB1-R) and further suppressed PI3K/Akt/mTOR." (PMID 35899228, 2022). "Compared with normal tissues, mTOR expression was downregulated in several types of carcinomas, especially KIRC, testicular tumors, and colon adenocarcinoma." (PMID 35082928, 2022).